MIR31HG (MIR31 host gene)
Diseases named in the same sentence as MIR31HG in open-access papers (continued):
Sharing a sentence is not in itself a finding about the gene and the disease.
thyroid cancer (3 papers, 2022 to 2023). "Using loss-of-function phenotype in SW579 and TPC-1 thyroid cancer cells, we first showed that suppression of MIR31HG affects cell growth, motility and apoptosis, indicating the implication of MIR31HG in thyroid tumorigenesis." (PMID 35443670, 2022). "Overexpression of MIR31HG was associated with malignant progression and high infiltration degree of immune cells in thyroid cancer." (PMID 36060239, 2022). "Here, we first uncovered that MIR31HG regulates miR-761 through pairing to miR-761, a low-expressed miRNA in thyroid cancer which has been identified as a strong suppressor in this disease." (PMID 35443670, 2022). "Here, we identified MIR31HG as a crucial regulator of thyroid cancer development in vitro and in vivo." (PMID 35443670, 2022). "Intriguingly, in thyroid cancer samples, we found a striking reduction of miR-761 expression and a significant inverse correlation between miR-761 and MIR31HG expression." (PMID 35443670, 2022). "Our findings also established the role of MIR31HG as a post-transcriptional regulator of MAPK1 through the shared binding sequence in miR-761, highlighting the MIR31HG/miR-761/MAPK1 axis in thyroid cancer." (PMID 35443670, 2022). "MIR31HG may promote cell growth and migration in lung, oral, or thyroid cancer cells, via the C/EBP/Wnt5A or MAP-kinase signaling pathways, depending on the specific cell types." (PMID 36980216, 2023). "Moreover, overexpression of MIR31HG in thyroid cancer cells (HTH83, SW579, and TPC-1) was validated by qRT-PCR compared to normal Nthy-ori 3–1 cells." (PMID 35443670, 2022). "MIR31HG was overexpressed in human thyroid cancer, and its overexpression predicted poor prognosis." (PMID 35443670, 2022). "Our findings also suggested the potential of MIR31HG as a biomarker for thyroid cancer prognosis." (PMID 35443670, 2022). "Therefore, we sought to elucidate the precise action of MIR31HG in the functional behaviors of thyroid cancer cells and its regulation through MIR31HG-mediated the activity of competing endogenous RNA (ceRNA)." (PMID 35443670, 2022). "Importantly, we demonstrated a novel regulatory mechanism, the miR-761/MAPK1 axis, in the regulation of MIR31HG in thyroid cancer." (PMID 35443670, 2022). "Interestingly, overexpression of MIR31HG has recently been found in thyroid cancer tissue samples." (PMID 35443670, 2022). "Taken together, these findings have identified the workings of an undescribed regulatory network, in which MIR31HG targets miR-761 to regulate the expression of MAPK1, leading to the alteration of the functional behaviors of thyroid cancer cells." (PMID 35443670, 2022). "Our findings demonstrate that MIR31HG targets miR-761 to regulate the functional behaviors of thyroid cancer cells by upregulating MAPK1, highlighting a strong rationale for developing MIR31HG as a novel therapeutic target against thyroid cancer." (PMID 35443670, 2022).
chordoma (2 papers, 2020 to 2022). Chordomas are rare malignant tumors arising from embryonic remnants of the notochord in axial skeleton. "have shown that MIR31HG was elevated in chordoma patients and MIR31HG silence repressed the migration, growth, and invasion of chordoma cells." (PMID 36506078, 2022). "For example, MIR31HG could enhance proliferation, migration and invasion by up-regulating EZH2/miR-31 and then indirectly activating the oncogene RNF144B in chordoma." (PMID 32280307, 2020).
colon cancer (2 papers, 2020). "In colon cancer, ILF3-AS1, together with LINC0184, AC105243.1, LOC101928168, MIR31HG, and AC006329.1, were revealed to be an independent predictive factor of colon cancer recurrence." (PMID 32117452, 2020).
esophageal cancer (2 papers, 2020 to 2022). A primary or metastatic malignant neoplasm involving the esophagus. "Previous studies have shown that MIR31HG presents a carcinogenic phenotype in various solid tumors, such as PDAC, squamous cell carcinoma of the head and neck, and esophageal cancer, while the effects of LINC01239 have rarely been reported." (PMID 35570408, 2022).
glioblastoma (2 papers, 2023 to 2024). The most malignant astrocytic tumor (WHO grade IV). "Triggered by STAT1, MIR31HG could transcribe β-catenin from the cytoplasm into the nucleus, and the Wnt/β-catenin pathway activator LiCl was utilized to invert both the ability to inhibit proliferation and impress apoptosis caused by MIR31HG knockdown in glioblastoma." (PMID 37636269, 2023). "In glioblastoma, MIR31HG could facilitate nucleus translocation and stimulate Wnt/β‐ catenin signaling cascade." (PMID 37950038, 2024). "Therefore, we can safely conclude that the activation of the Wnt/β-catenin signaling pathway regulated by MIR31HG enhances cell growth in glioblastoma." (PMID 37636269, 2023).
glioma (2 papers, 2015 to 2021). A benign or malignant brain and spinal cord tumor that arises from glial cells (astrocytes, oligodendrocytes, ependymal cells). "In low grade gliomas (LGG), 6.96% were MIR31HG−/−, 27.04% were MIR31HG+/−, and 66.00% were MIR31HG+/+." (PMID 26164206, 2015).
laryngeal squamous cell carcinoma (2 papers, 2021 to 2022). A squamous cell carcinoma that arises from the larynx. "Similar findings have been reported in laryngeal squamous cell carcinomas for other binomial LncRNA/mRNA transcripts, such as: NR_003919/PIK3R1, NR_027340/ITGB1, MIR31HG/HIF1A, and SOX2‐OT/DDIT4." (PMID 33433063, 2021).
lymph node metastasis (2 papers, 2020 to 2023). "The association between MIR31HG and clinicopathologic features, including clinical stage, lymph node metastasis (LNM), distant metastasis (DM), and tumor size were further analyzed by ORs and their 95% CIs." (PMID 32280307, 2020). "Numerous studies have revealed that MIR31HG is positively related to clinicopathological features, including tumour size, clinical stage, TNM stage, advanced T category, lymph node metastasis, distant metastasis, overall survival, and progression-free survival." (PMID 37636269, 2023).
pancreatic cancer (2 papers, 2020 to 2022). "Previously, only one study investigated the role of MIR31HG in pancreatic cancer, which found that MIR31HG is overexpressed in PDAC tissues and cell lines." (PMID 35743003, 2022). "In addition, it was reported that MIR31HG could function as an oncogene that promotes pancreatic cancer progression, by acting as an endogenous sponge competing for miR-193b." (PMID 33334367, 2020).
thyroid (2 papers, 2022 to 2024). "With our findings, we envision that targeting MIR31HG may have the potential to prevent and inhibit thyroid tumorigenesis." (PMID 35443670, 2022). "However, the activity of MIR31HG in thyroid carcinogenesis has not yet been defined." (PMID 35443670, 2022).
cyst (1 paper, 2022). A sac-like closed membranous structure that may be empty or contain fluid or amorphous material. "Despite this uncertainty, activation of this 5’ enhancer with MIR31HG upregulation in the ADPKD collecting duct is consistent with the notion that MIR31HG may promote cyst growth via suppression of cellular senescence." (PMID 36310237, 2022). "This suggests that MIR31HG may promote cyst growth through suppression of senescence and adaptation to hypoxia." (PMID 36310237, 2022).
Obesity (1 paper, 2017). Accumulation of substantial excess body fat. "Our study indicating the role of MIR31HG in adipocyte commitment may also provide a potential target for the treatment of obesity through subcutaneous injection of shMIR31HG." (PMID 28808264, 2017).
oropharyngeal cancer (1 paper, 2017). Carcinoma, predominantly squamous cell, arising from the epithelial cells of the oropharynx. "In our study, MIR31HG expression does not appear to be significantly different between HPV-positive OPC (oropharyngeal cancer) and HPV-negative OPC (P = 0.02, lower in HPV-positive OPC)." (PMID 28415559, 2017).
retinoblastoma (1 paper, 2018). A malignant tumor that originates in the nuclear layer of the retina. "The results of microarray analysis showed that lncRNAs HOTAIR, CCAT1, DNM3OS, HIF1A‐AS1, MEG3 and 7SK expressions were up‐regulated, and lncRNAs PCAT1, MIR31HG, BCAR4, RRP1B and H19 were down‐regulated within retinoblastoma tissues." (PMID 30030888, 2018).
synovitis (1 paper, 2021). Inflammation of a synovial membrane. "Taken together, our data suggest that MIR31HG plays a protective role in RA-induced synovitis." (PMID 34753831, 2021).
vulvar squamous cell carcinoma (1 paper, 2020). An invasive squamous cell carcinoma arising from the vulva. "For instance, in vulvar squamous cell carcinoma, MIR99AHG and MIR31HG expressions are correlated and associated with tumor differentiation." (PMID 32079618, 2020).
tumor (23 papers, 2015 to 2025). "In detail, high expression of MIR31HG was associated with poor tumour stages and distant metastasis." (PMID 37636269, 2023). "This complex SV led directly to the loss of the CDKN2A tumor suppressor signaling pathway and significantly upregulated the expression of the MIR31HG gene in its neighboring region." (PMID 35570408, 2022). "Due to its potential clinical relevance as a marker, the expression of MIR31HG and its underlying biological functions could be vital to the tumor." (PMID 33334367, 2020). "Furthermore, MIR31HG expression was remarkably associated with survival time, tumor-node metastasis (TNM) stage and carcinogenesis of certain cancers." (PMID 32280307, 2020). "Herein we characterize miR-31 as a novel tumor suppressor encoded by the MIR31HG gene." (PMID 26164206, 2015). "For instance, LncHIFCAR (formerly known as MIR31HG) activates hypoxia-related signaling pathways, such as glycolysis and metabolic reprogramming, and promotes tumor growth and metastasis by directly binding to HIF-1α to form a complex." (PMID 40861273, 2025). "Findings on MIR31HG expression in tumor tissues and its roles in malignant disease development are controversial." (PMID 37950038, 2024). "Ki67 staining of tumor bulk indicated that ASO therapy remarkably slowed cell proliferation while MIR31HG overexpression promoted Ki67 indicated cellular proliferation in vivo." (PMID 37950038, 2024). "Next, we tested the role of MIR31HG in tumor initiation and progression in vivo using a mouse model." (PMID 37950038, 2024). "Previously identified MIR31HG targets include hypoxia-inducible factor (HIF)-1α, p21, miR-193b, miR-214, miR-361-3p, and miR-761, and these are associated with tumor growth, metastasis, and chemoresistance." (PMID 35743003, 2022). "MIR31HG was overexpressed in PDAC tumor tissues according to The Cancer Genome Atlas (TCGA) PanCancer Atlas dataset." (PMID 35743003, 2022). "Examples of MIR31HG as a potential tumor promoter include malignant melanoma and cervical carcinoma, where it is present at high levels." (PMID 35443670, 2022). "Analysis of MIG31HG expression in primary cancer samples to paired thyroid samples, using qRT-PCR of total RNA preparations, showed that MIR31HG expression was at high levels in tumor tissues." (PMID 35443670, 2022). "Here, we found that overexpression of YY1 reversed the anti-tumor effect mediated by MIR31HG knockdown and that YY1 positively promoted MIR31HG expression." (PMID 34485123, 2021). "As a result, these results demonstrated that MIR31HG functioned as an oncogene to promote tumor progression, and MIR31HG/miR-193b axis served as a potential therapeutic target for PC." (PMID 34760707, 2021). "P16 (INK4A) is a well-known tumor suppressor, MIR31HG was reported to negatively regulate p16-dependent senescence phenotype, suggesting a potential role in carcinogenesis." (PMID 32280307, 2020). "Furthermore, ASO-mediated MIR31HG-targeting therapy significantly attenuated tumor metastasis in distant organs, including the lungs and liver, whereas MIR31HG overexpression remarkably promoted metastasis in vivo." (PMID 37950038, 2024). "Through ceRNA mechanisms, MIR31HG could act as a miRNA sponge to regulate the expression of downstream messenger RNAs (mRNAs), and affect tumour progression." (PMID 37636269, 2023). "In summary, MIR31HG exerted oncogenic function by directly regulating miR-361 for tumour growth." (PMID 37636269, 2023). "Furthermore, MIR31HG expression seemed to share a strong relationship with clinical characteristics in a number of cancers, such as tumour node metastasis (TNM), differentiation, distant metastasis, disease-free survival (DFS), and overall survival (OS)." (PMID 37636269, 2023). "In addition, they identified that a tumor-suppressive miR-193b directly targets MIR31HG, and MIR31HG also competes for miR-193b binding to its messenger (m)RNA targets." (PMID 35743003, 2022).
tumor (continued). "Consistently, MIR31HG was found to be overexpressed in tumor tissues in these two cohorts." (PMID 35743003, 2022). "Additionally, increased expression of MIR31HG has been demonstrated to promote tumor progression and reduce the efficacy of gefitinib in NSCLC." (PMID 36060239, 2022). "Depending on the cancer type, MIR31HG can be either oncogenic or tumor-suppressive." (PMID 35743003, 2022). "Additionally, overexpressing MIR31HG significantly increased the KI67-positive cell rate, indicating that MIR31HG promotes tumor cell proliferation (P<0.05)." (PMID 34485123, 2021). "In contrast, MIR31HG was found to be highly expressed in cells lines and clinical tumor samples with the basal subtype compared to luminal and other subtypes, indicating that MIR31HG not only shows tissue specific, but also subtype-specific overexpression in MIBC." (PMID 33334367, 2020). "To determine the clinical significance of LUCAT1, UCA1, and MIR31HG in HNC, we evaluated the associations of molecular expression with clinical presentations to assess their predictive power in diagnosis and prognosis using TCGA-HNSC data of the 43 HNC patients with paired normal and tumor samples." (PMID 36980216, 2023). "Five oncogenic (LUCAT1, MIR31HG, UCA1, HIF1A-AS2, and SUMO1P3) and tumor-suppressive (LINC00312) lncRNAs were independently validated, and three key molecules were further examined." (PMID 36980216, 2023). "It is also reported that MIR31HG expression was down-regulated in BLCA cell lines and tumor tissues." (PMID 33334367, 2020).
cancer (21 papers, 2015 to 2025). A tumor composed of atypical neoplastic, often pleomorphic cells that invade other tissues. "To explore the potential mechanism linking MIR31HG to PDAC subtypes, we compared the cancer hallmark enrichment results between MIR31HG-high vs. MIR31HG-low and basal-like subtype vs. classical subtype in the TCGA-PAAD dataset." (PMID 40065368, 2025). "In this study, cancer genomics data mining revealed that MIR31HG overexpression was positively associated with poorer disease-free survival and a transforming growth factor β (TGFβ)-induced EMT gene signature in PDAC patients." (PMID 35743003, 2022). "Given the prognostic significance of MIR31HG in cancers, in the current study, we firstly explored the association between MIR31HG level and clinical outcomes by performing a meta-analysis containing seventeen literatures with 2573 patients." (PMID 32280307, 2020). "Acting as an oncogene and a poor prognostic indicator, MIR31HG is overexpressed in various cancers, including PDAC." (PMID 40065368, 2025). "A large proportion of recent studies have indicated that MIR31HG has biological functions by triggering various signalling pathways in the pathogenesis of human diseases, especially cancers." (PMID 37636269, 2023). "A pan-cancer analysis of gene expression was performed by the UALCAN database using The Cancer Genome Atlas (TCGA) data to determine the expression of MIR31HG in human cancers." (PMID 37636269, 2023). "Cellular studies further demonstrated that MIR31HG facilitates areca nut-induced cancer progression, as silencing this molecule attenuated arecoline-induced invasion ability in HNC cells." (PMID 36980216, 2023). "First, to determine the expression of MIR31HG in human cancers, the UALCAN database was used to investigate the pancancer expression of MIR31HG." (PMID 37636269, 2023). "It was reported that a high level of MIR31HG contributes to the progression of a variety of cancers by activating canonical Wnt signaling, which is also recognized as the Wnt/β-catenin signalling pathway." (PMID 37636269, 2023). "The oncogenic property of MIR31HG was also identified in PDAC, in which MIR31HG promotes cancer cell proliferation and invasion." (PMID 35743003, 2022). "It has been reported that miR-193b is able to directly target MIR31HG, resulting in cancer progression by counteracting miR-193b in pancreatic cancer." (PMID 34489556, 2022). "MIR31HG is frequently upregulated in various cancer types, including PDAC, and serves as an oncogene and a poor prognostic factor." (PMID 35743003, 2022). "MIR31HG is markedly upregulated in cancer tissues, with potential roles in cancer initiation, progression, and metastasis." (PMID 34489556, 2022). "Conversely, elevated expression of MIR31HG hinders the growth and motility of hepatocellular carcinoma cells, highlighting its cancer suppressive activity." (PMID 35443670, 2022). "The MIR31 host gene (MIR31HG) is a newly identified long non-coding (lnc)RNA that exhibits ambiguous roles in cancer." (PMID 35743003, 2022). "Accordingly, down-regulated MIR31HG expression was found in cancer tissues compared to normal tissues, which supports expression results measured by qPCR from a previous study." (PMID 33334367, 2020). "In NSCLC, MIR31HG behaved as an oncogene by inhibiting miR-214 expression, thereby facilitating cancer cell migration and invasion." (PMID 32280307, 2020). "Emerging studies have explored the prognostic value of MIR31HG in cancers, but its role remains elusive." (PMID 32280307, 2020). "As the host gene of miR-31, MIR31HG was firstly identified to co-express or modulate the expression of miR-31 in certain cancers." (PMID 32280307, 2020). "On the contrary, overexpression of MIR31HG was closely associated with favorable OS and DFS in gastrointestinal cancer, indicating a tissue-specific predictive prognosis of MIR31HG in multiple human cancers." (PMID 32280307, 2020).